TGFB2 (transforming growth factor beta 2)
Diseases named in the same sentence as TGFB2 in open-access papers (continued):
Sharing a sentence is not in itself a finding about the gene and the disease.
tumor (continued). "Secondly, we identified imperatorin as a novel inhibitor of TGFβ2 and tumor metastasis." (PMID 32832354, 2020). "In this report, we assessed the expression of TGFβ2 as it related to the prognosis of 33 different types of cancers using the independent Oncomie and GEPIA databases, revealing clear differences between tumour and normal tissue expression of TGFβ2 in many cancers." (PMID 32530106, 2020). "Additionally, the Transforming Growth Factor-Beta 2 (TGFb2) is a versatile cytokine with a prominent role in cell migration, invasion, cellular development and immunomodulation and it promotes tumor malignancy." (PMID 33255335, 2020). "Western blot data showed that TGFβ2 was significantly upregulated in all of the metastatic cell sublines, compared with parental cells, suggesting that TGFβ2 is essential to drive tumor metastasis." (PMID 32832354, 2020). "We also detected TGFβ2 expression in 12 pairs of ESCC primary tumor tissues and matched non‐tumor tissues by Western blot, and the results revealed that TGFβ2 is overexpressed in the majority of ESCC tumors (9 cases/12 cases, 75.0%), compared with matched normal tissues." (PMID 32832354, 2020). "Kaplan–Meier survival analysis indicated that the patients with high TGFβ2 expression had significantly shorter survival (median survival = 13.0 months) than the patients with lower tumor TGFβ2 expression (median survival = 25.0 months) (log‐rank = 5.65, P < 0.05)." (PMID 32832354, 2020). "Although bioinformatic analyses and in vitro findings shed new light on the mechanistic understanding of tumor-suppressive miR-7-5p and its target TGFβ2 in OC metastasis, the conclusions of this study need to be further confirmed in future studies based on in vivo experimental validations." (PMID 33100909, 2020). "At the same time, the transcript levels of genes encoding for claudin-3 (CLDN3), the nuclear receptor subfamily 4 group A member 1 (NR4A1), and the transforming growth factor β (TGFB2) related to angiogenesis, hypoxic response and tumor invasion were up-regulated." (PMID 32664456, 2020). "The TGFB2 protein suppresses tumor growth by regulating cell growth, proliferation, and apoptosis." (PMID 32899474, 2020). "Interestingly, comparative Sanger analysis of the DNA from blood and tumor DNA at the positions of rs7587470101 in TGFB2, and rs139924814 and rs3219143 in PARP1, revealed an over‐representation of the paternally inherited allele in the tumor." (PMID 30680959, 2019). "Due to the interesting decrease in the TGFβ2 levels between the NOF and CAF, we investigated whether TGFβ2 induces EMT in tumor cells as well." (PMID 29221185, 2017). "The physiological effect of elevated TGFB2 on the tumour could potentially result in increased extravasation but which is reduced following HSP90 inhibition." (PMID 27563925, 2016). "Finally, we show that the early adaptive drug-resistant EGFR-mutant tumor cells under reprogrammed transcriptomic/metabolomics profiles can be secondarily targetable in principle, and are vulnerable to TGFβ2 inhibition, and glutamine-depletion." (PMID 27852038, 2016). "We determined that tumor cell-cell contact on bone marrow stroma is necessary for LuCaP PDX cells to proliferate in vitro and was associated with a universal downregulation of TGFB2." (PMID 26090669, 2015). "Since several key genes in the pathway were overexpressed in tumor tissues, including TGFB2, TGFBR1, SMAD2, and SMAD4, TGFβ signaling pathway may be involved in the pathogenesis of fibroblastic meningioma." (PMID 23285163, 2012).
tumor (continued). "Notably, triple blockade of tRF‐22, TGFβ2, and PD‐1 nearly eradicated tumor lesions." (PMID 41144758, 2026). "However, in the advanced stage, tumor cells may gradually lose their response to tumor‐inhibitory signals of TGFβ2 and instead respond to signals that promote tumor progression, such as those that enhance tumor invasion and metastasis." (PMID 40151835, 2025). "They showed that high TGFB2 mRNA levels were associated with an immunologically “cold” tumor microenvironment (TME), characterized by low expression of antigen-presenting cell (APC) markers (e.g., CD14, CD163, ITGAX/CD11c), which impairs anti-tumor immune responses." (PMID 41373732, 2025). "In contrast, TGFB2 appears to have a more unidirectional or context-specific impact—its high expression negatively impacts overall survival, particularly in younger patients, perhaps by more directly shaping a fibrotic and immunosuppressive tumor microenvironment." (PMID 40650134, 2025). "Furthermore, Oil red O staining of tumor tissue indicated that TGFB2 knockdown could decrease lipid accumulation." (PMID 38914663, 2024). "The expression of TGFβ2 secreted by osteoblasts was markedly upregulated during osteoblast differentiation and induced prostate tumour dormancy in vitro and in vivo, indicating that osteoblast differentiation may affect tumour dormancy." (PMID 36307871, 2022). "Finally, it is possible that other extracellular cues besides TGFB2 provided by the tumor environment might affect JUNB signaling in cancerous cells and, thereby, their tumorigenicity." (PMID 36494864, 2022). "Low endogenous levels of another ligand of the TGFβ superfamily, TGFβ2, in the lungs has also been proposed as a mechanism supporting the outgrowth of disseminated tumor cells and may explain the short latency of metastatic foci in the lungs compared with other organs." (PMID 33014869, 2020). "The major cell type expressing MMP9 mRNA and protein were tumor‐infiltrating neutrophils, while Tgfb1 mRNA expression was mostly restricted to tumor‐infiltrating monocytes and Tgfb2, and Tgfb3 mRNA expression was mostly restricted to tumor epithelium and stroma." (PMID 31793740, 2020). "In addition, allelic imbalances of PARP1 and TGFB2 were detected in the tumor of the proband." (PMID 30680959, 2019). "Due to the assessed transcriptome changes and upregulation of TGFB1 and TGFB2 itself, it is suggested that knockdown of ERβ resulted in activation of TGFβ1/2 signaling, which resulted in induction of genes with known functions in extracellular matrix and tumor cell invasion." (PMID 28003019, 2016). "These stromal cells include tumour fibroblasts, which express growth factors such as TGFβ2 that act on the adjacent tumour cells, as well as proteins of the extracellular matrix, which are modified by matrix metalloproteinases derived from tumour cells to regulate tumour invasion and angiogenesis." (PMID 22415295, 2012). "Transforming growth factor beta 2 (TGFβ2), known primarily for its growth-inhibitory properties, is both a suppressor and promoter of tumorigenesis, producing a malignant phenotype in tumor-derived cells in culture and exhibiting high expression levels in advanced tumors." (PMID 21246056, 2011). "tRF‐22 fosters an immunosuppressive and pro‐oncogenic tumor microenvironment in ESCC by stabilizing hnRNPAB against TRIM25‐mediated ubiquitination and enhancing TGFβ2 expression, which increases PMN‐MDSCs infiltration and suppresses CD8+ T cells." (PMID 41144758, 2026). "In vivo, tRF‐22 overexpression resulted in tumor growth accompanied by an increase in PMN‐MDSCs and a decrease in CD8+ T cells, while these effects were mitigated by silencing HNRNPAB or TGFB2, or by applying anti‐TGFβ antibody." (PMID 41144758, 2026). "Both TGFB2 and IL6 appear to serve as robust predictors in PDAC because they more directly drive and reinforce a tumor microenvironment that promotes aggressive disease." (PMID 40650134, 2025).
tumor (continued). "The convergence of these pathways means that when both TGFB2 and IL6 are upregulated, their cooperative effects on the tumor stroma and the immune system are accentuated, rendering them particularly predictive of poor outcomes in PDAC." (PMID 40650134, 2025). "Tumor-derived VEGFA and TGFβ2 signals were received by NRP2 and TGFβR2/3 receptors present on MES and RG-PC cells, respectively, with PDGFA_PDGFRA signaling from tumor cells directing final PC specification." (PMID 40562749, 2025). "Blocking the METTL1–TGF-β2–PMN-MDSC axis (e.g., via anti-Ly6G antibody, hepatocyte-specific METTL1 or Tgfb2 knockdown, or inhibition of TGF-β signaling) markedly attenuates iRFA-induced tumor progression and restores CD8+ T cell levels." (PMID 41562049, 2025). "Monitoring DNA methylation of TGFB1, TGFB2, and TGFB3 provides a robust method for characterizing tumor microenvironments and selecting candidates for immunotherapy in cold tumors." (PMID 40565031, 2025). "Future studies will require confirmation of mRNA levels validated using qPCR methods, protein levels, and signaling mechanisms to expand on these initial findings, especially utilizing TGFB2 and MGMT methylation screens from patient-derived tumor tissues." (PMID 40338274, 2025). "TGFβ2 is also involved in the EMT process of various malignant tumors, conferring highly invasive migratory abilities to tumor cells." (PMID 40151835, 2025). "TGFB isoforms, particularly TGFB2, play pivotal roles in PDAC progression by modulating key mechanisms such as immunosuppression, angiogenesis, metastasis, and the tumor microenvironment." (PMID 40650134, 2025). "These present studies detail the interaction between TGFB2 and IFNGR2 in the tumor microenvironment, resulting in a prognostic impact on OS outcomes in pbDMG patients." (PMID 38255296, 2024). "Mechanistically, tumor paracrine TGFβ2 signaling decreases the expression of AMBRA1 in keratinocytes and disrupts epidermal integrity, facilitating tumor ulceration and/or metastasis." (PMID 39201498, 2024). "In the present study, we found that TGFβ2 was the major isoform that overexpressed in TNBC cell lines and tumour samples both in vitro and in vivo." (PMID 38299307, 2024). "NT5E (CD73), CSF ligands, CD274 (PDL1), IL1B, IL6, and IL10 transcripts were primarily found in the peri necrotic zone, whereas NOS2 (iNOS), TGFB2, and NOX1 expression is localized to cellular tumor regions." (PMID 39272914, 2024). "Among the predicted miRNAs potentially targeting TGFβ2, we found miRNAsTGFβ2 levels were inversely correlated with TGFβ2 levels in TNBC cell lines, patient tumour tissues and serums." (PMID 38299307, 2024). "In this study, we found that TGFβ2 was the major isoform that was overexpressed in TNBC cell lines, tumour samples and serum." (PMID 38299307, 2024). "Previous researches has indicated that TGFβ2 is connected to the prognosis of CRC and can contribute to the tumor progression of and resistance to 5-Fu." (PMID 38779664, 2024). "In this study, we demonstrate that TGFB2 expression is abnormally elevated in gemcitabine-resistant PDAC cells, and patient-derived xenograft (PDX) models, even clinical tumor tissue." (PMID 38914663, 2024). "One study found that TGFB2, through MMP-2 expression, supported tumor cell invasion by breaking down the basal membrane." (PMID 38539537, 2024). "Nuclear FAK has been shown to promote tumor progression by regulating the transcription of cytokines/chemokines, including CCL5, TGFβ2, IL33, and VEGFβ, which in turn drive the establishment of an immunosuppressive microenvironment." (PMID 37845206, 2023). "RNAseq-based high TGFB2 mRNA level was an indicator of poor prognosis for DIPG patients, but not for pediatric GBM patients or pediatric DMG patients with tumor locations outside of the pons/brainstem." (PMID 36980562, 2023).
tumor (continued). "Blocking ATX activity changed the phenotype of the mice by decreasing the plasma concentrations of CXCL9, CXCL10, and CCl2 and the tumor concentrations of LIF, TGFβ1, TGFβ2, and prolactin." (PMID 37296899, 2023). "RNAi therapeutics targeting TGFB2, including S-ODN, may disrupt the TGFB2-linked signaling networks that promote the proliferation and survival of TGFB2high DIPG cells, lift TGFB2-induced suppression of anti-DIPG immunity, as well as block the Treg-mediated tumor tolerance." (PMID 36980562, 2023). "Both TGFB2 and TGFBR3 are directly involved in TGFβ signalling, which regulates many different aspects of tumour formation and progression." (PMID 37391533, 2023). "In HCC, overexpression of EZH2 represses miR-622 through H3K27me3 deposition and results in CXCR4 upregulation and unfavorable prognosis, while BMI1 enhances TGFβ2/SMAD pathway and facilitates tumor cell proliferation and cell cycle progression." (PMID 36566204, 2022). "A positive correlation of the Hypoxia_DEGs_Score with the expression of TGFB1 and TGFB2 suggests that the hypoxic status of HCC results in a tumor immunosuppressive state with increased infiltration of immunosuppressive cells." (PMID 36059442, 2022). "The TGF-β protein family has complex functions in a wide range of regulatory pathways, among which TGFβ2 is a T cell suppressor in tumor microenvironment of GBM and is expressed in about 90% of GBM tumor cells." (PMID 35135556, 2022). "The same tissue and tumor type are seen with the Cys291Trp in the ligand of INHA that shares β8Cys@1 and β8Cys@4 with TGFB2." (PMID 36214621, 2022). "For example, BMSCs, one subtype of bone stromal cells, can either promote or impede the progression of tumor dormancy by secreting BMP7, TGFβ2, GAS6." (PMID 34712663, 2021). "In lymph node metastases compared to the invasive front of the tumor, ONECUT2 and SOX2 were down-regulated, while PTPN13, TGFB2, ZEB2, RND3 and CDKN1B were up-regulated." (PMID 34046357, 2021). "Next, we focused on one distinctive gene cluster that contained transforming growth factor beta 2 (TGFB2) and interleukin-10 (IL10), which appeared to be driven by the recurrence of selective copy number gain in multiple tumor types." (PMID 34344966, 2021). "The neutrophils secrete several inflammatory, immunoregulatory and angiogenic factors, including NE, PR3, CathG, MMPs, VEGF, Bv8 (prokineticin 2), oncostatin M, IL-1β, TGFβ2, BMP2 and HGF, that modulate the tumor microenvironment and affect tumor growth." (PMID 34572138, 2021). "To further select the key genes in the complex network, we analyzed all of genes integrating with the clinical categories and found that TGFβ2, GNG11, PDGFB, and ITGA5 were changed among different patients’ tumor stages, states, T categories, and grades." (PMID 33115518, 2020). "These two genes’ (TGFB2 and CCNA2) relationship with platelets and immunity has been reported by many tumor-related studies." (PMID 33195410, 2020). "In recent researches, it was reported that tumor-associated macrophages (TAMs) could secret TGFβ1 to promote LCSC properties by inducing EMT, and tumor-associated neutrophils (TANs) could secret TGFβ2 and BMP2, which induce miR-301b-3p and enhance stem cell characteristics in HCC." (PMID 33292618, 2020). "High TGFβ2 expression in ESCC correlates with metastasis and patient survival, and functionally contributes to tumor metastasis via activating extracellular signal‐regulated kinases (ERK) signaling." (PMID 32832354, 2020). "Our final finding suggested that invasive tumor cells induced perforin downregulation within SN by ICAM-1 and TGFβ2 signaling." (PMID 29966014, 2018). "We have previously discovered and/or characterized tumor-specific DNA methylation of six genes (APC, GSTP1, HOXD3, KLK10, TBX15, and TGFβ2) in radical prostatectomy tumor samples." (PMID 30470249, 2018).
tumor (continued). "Accordingly, we were able to demonstrate tumor escape using supernatant from the muscle invasive UBC cell line (5637), where the supernatant contained soluble ICAM-1 and TGFβ2 that induced perforin downregulation." (PMID 29966014, 2018). "TGFB2, which initiates the MAPK signaling pathway, is known as a tumor suppressor, but in advanced disease, it appears to promote tumor progression." (PMID 30279327, 2018). "As a novel synergistic tumor immune escape was exerted by ICAM-1 and TGFβ2 signal, it opens a new potential in translational application." (PMID 29966014, 2018). "The limitation of this study was that only two signals out of ~20 signals (expressed only by invasive tumor cells) from the proteomic analysis was validated (ICAM-1 and TGFβ2)." (PMID 29966014, 2018). "It was observed an enrichment of MAPK-related genes, represented in our results by upregulation, in the tumor samples, of TGB1, TGFB2 and TGFBR1 that were shown to activate the MAPK pathway." (PMID 28490781, 2017). "Each specimen was examined by qRT-PCR analysis for the expression of 3 tumor-related transcripts (PAX3d, MITF-m and TGFB2) at diagnosis, and at the following 6 and 12 months during clinical monitoring." (PMID 29156734, 2017). "TGFB2 is a member of the TGFB family, which has tumor promoting functions enhancing the epithelial-mesenchymal transition and evasion of immunity." (PMID 28506304, 2017). "A similar adverse link was observed between RFS and the expression of TGFB2 and TGFB3 genes by tumor cells, with the latter representing one of the strongest indicators of a poor clinical outcome." (PMID 27215396, 2016). "Inhibition of HSP90 also led to a specific increase in transforming growth factor beta 2 (TGFβ2) levels in CAF; Conclusions: We suggest that HSP90 inhibitors act not only upon tumour cells, but also on CAF in the tumour microenvironment." (PMID 27563925, 2016). "Our PCR array data showed that both M1-related genes (Ccl2, Ccl3, Ccl4, Ccl5, Il12b, Il1b and Ccl1) and M2-related genes (Il10, Tgfb2 and Il1rn) were significantly upregulated in NM11-shsST2 tumours compared with NM11-shCont tumours." (PMID 27882929, 2016). "Tumor stromal pathways are also in evidence with the common genes including; TLR4, TLR7, HLA-DRA, HLA-DQA1, CXCR4, FOS and TGFB2 (immune surveillance and chemokine pathways) and NF2, ITGA7, PGF, ITGA4, PDGFD and PARVA (focal adhesion)." (PMID 23226201, 2012). "We have recently described the involvement of TGFβ2, IDO, and PDL-1 on GBM immunosuppressive properties on T-cell functions in a tumour-specific T-cell model." (PMID 20953324, 2010). "Moreover, TGFβ2 crucially regulates epithelial–mesenchymal transition (EMT), promoting tumor metastasis via transcriptional and posttranscriptional mechanisms." (PMID 40151835, 2025). "In tumor-derived stromal cultures, TGFB1 and TGFB2 levels were strongly correlated (r = 0.976)." (PMID 41373732, 2025). "Additionally, a differential expression of the cytokine genes CCL2, CCL20, TGFB1, and TGFB2; the transcription factor gene IRF4; and the receptor genes CCR2, IL10RB, TGFBR1, and TGFBR2 was identified in tumor tissue and vestibular nerve tissue." (PMID 39272860, 2024). "In line with the known role of TGFβ2, our in vitro knockdown of TGFβ2 impacted on migration and invasion rather than proliferation, and it was particularly important in the in vivo tumor setting." (PMID 39327614, 2024). "Thus overexpression of lncRNA TGFB2- AS1 significantly inhibited the enrichment of SMARCA4 in the TGFB2 promoter region, which in turn inhibited TGFB2 transcription and suppressed tumor growth and lung metastasis." (PMID 39022688, 2024). "TGFβ2 shRNA knockdown tumors displayed reduced growth compared with scrambled control shRNA, corroborating that TGFβ2 is also important for TNBC tumor development and aggressiveness in vivo." (PMID 39327614, 2024).